CCDC124 (coiled-coil domain containing 124)
Description:
Ribosome-binding protein involved in ribosome hibernation: associates with translationally inactive ribosomes and stabilizes the nonrotated conformation of the 80S ribosome, thereby promoting ribosome preservation and storage. Also required for proper progression of late cytokinetic stages.
Synonyms: Lso2; oxs1
Tractability: Small molecule: a structure with a bound ligand is known. Antibody: its Gene Ontology location is reachable by antibodies, with high confidence; the Human Protein Atlas places it where antibodies can reach. PROTAC: ubiquitination databases record sites on it; its protein half-life has been measured.
Gene: Protein-coding gene on chromosome 19 (17,932,588 to 17,944,914, forward strand). Ensembl gene ENSG00000007080.
Subcellular location: Cytoplasm, cytoskeleton, microtubule organizing center, centrosome; Midbody
Subcellular location (Human Protein Atlas): Plasma membrane; Cytosol
Gene Ontology:
Molecular function: protein binding; RNA binding; transcription coactivator activity
Biological process: transcription by RNA polymerase II; positive regulation of DNA-templated transcription
Cellular component: cytosol; midbody; plasma membrane; nucleus; centrosome
Genetic constraint (gnomAD): Loss-of-function variants: 9 observed, 15.84 expected, observed/expected ratio (o/e) 0.57, 90% interval 0.34 to 0.99. The upper end of that interval is the gene's LOEUF score, 0.99, which puts it in group 4 of 6, group 1 being the genes least tolerant of losing a copy. Missense variants: 284 observed, 292.89 expected, observed/expected ratio (o/e) 0.97, 90% interval 0.88 to 1.07. Synonymous variants: 126 observed, 118.12 expected, observed/expected ratio (o/e) 1.07, 90% interval 0.92 to 1.24.
Homologues: Orthologues: chimpanzee CCDC124 (100% identical), macaque CCDC124 (99% identical), dog CCDC124 (96% identical), pig CCDC124 (95% identical), guinea pig CCDC124 (90% identical), mouse Ccdc124 (87% identical), rat Ccdc124 (87% identical), tropical clawed frog ccdc124 (73% identical), zebrafish ccdc124 (69% identical), Caenorhabditis elegans Y73E7A.1 (48% identical), Drosophila melanogaster CG6013 (42% identical).
Diseases named in the same sentence as CCDC124 in open-access papers:
CCDC124 is named in the same sentence as 10 diseases in open-access papers, as found by Europe PMC text mining. Sharing a sentence is not in itself a finding about the gene and the disease. The quoted sentences say what the papers report.
autoimmune disease (1 paper, 2025). A disorder resulting from loss of function or tissue destruction of an organ or multiple organs, arising from humoral or cellular immune responses of the individual to their own tissue constituents. "Although CCDC124 has primarily been studied in the context of cancer, its roles in regulating cytokinesis and translation during mitosis may be critically relevant in autoimmune diseases such as RA, where aberrant immune function and cell division are observed." (PMID 40700276, 2025).
colorectal cancer (1 paper, 2021). A primary or metastatic malignant neoplasm that affects the colon or rectum. "According to the previous reports, CCDC124 was significantly overexpressed in endometrial cancer (EC), hepatocellular carcinoma (HCC), colorectal cancer (CRC), and ovarian cancer (OC) was related to tumor cell division, tumor heterogeneity and drug resistance." (PMID 35096017, 2021).
malnutrition (1 paper, 2023). Inadequate nutrition resulting from poor diet, malabsorption, or abnormal nutrient distribution. "The yeast late-annotated short open reading frame 2 (Lso2) is another declamping factor involved in translational recovery following malnutrition during stationary phase with a comparable function to its mammalian counterpart, a coiled-coil domain containing short open reading frame 124 (CCDC124)." (PMID 37427381, 2023).
urinary bladder cancer (1 paper, 2025). A primary or metastatic malignant neoplasm involving the bladder. "Upregulation of the CCDC124 gene was noted in cases of cancer, and its mRNA levels are considered molecular prognostic signatures in breast, ovarian, endometrial, and urinary bladder cancers." (PMID 40700276, 2025).
CCDC124 also shares sentences with these, for which no sentence is quoted: cancer (1 paper); endometrial cancer (1); hepatocellular carcinoma (1); infection (1); ovarian carcinoma (1); tumor (1).